STAT3 (signal transducer and activator of transcription 3)
Diseases named in the same sentence as STAT3 in open-access papers (continued):
Sharing a sentence is not in itself a finding about the gene and the disease.
colorectal cancer (continued). "Therefore, miR-27a could be a useful biomarker for colorectal cancer development and progression, and also could have a therapeutic potential targeting SGPP1, Smad2 and Stat3 for colorectal cancer therapy." (PMID 25166914, 2014). "In conclusion, for the first time we demonstrate that Spica Prunellae inhibits colorectal cancer growth in vivo via promoting the apoptosis of cancer cells, inhibition of proliferation and anti- angiogenesis, which is mediated by the suppression of the STAT3 pathway." (PMID 23800091, 2013). "Therefore, these prompted us to evaluate the antiangiogenic and anticancer activities of AL and to fully elucidate its molecular mechanisms with special focus on STAT3 signaling pathway in human umbilical vein endothelial cells (HUVECs) and colorectal cancer cells." (PMID 23848964, 2013). "Research has shown that the overexpression of zinc finger protein 263 (ZNF263) markedly promotes the proliferation, invasion, migration, and EMT of colorectal cancer (CRC) cells, concomitantly elevating STAT3 expression and mRNA stability." (PMID 40772037, 2025). "In colorectal cancer, hyperactivating UHMK1/STAT3 positive feedback loop contributes to colorectal cancer cell proliferation and chemoresistance." (PMID 40918462, 2025). "miR‐15 also promoted the malignant phenotypes of colorectal cancer by increasing PTEN/AKT and STAT3/TWIST1 signaling pathways." (PMID 39901895, 2025). "STAT3 induced expression of the secreted glycoprotein LRG1 promotes invasion and metastasis in colorectal cancer models, and LRG1 also induces metastasis of melanoma cells via STAT3 activation." (PMID 40597443, 2025). "EGCG treatment inhibited STAT3 and CXCL8 expression and NETs formation in colorectal cancer-derived neutrophils." (PMID 41019086, 2025). "Previous studies have shown that TRIM family proteins regulate colorectal cancer cell proliferation, migration, and invasion through the JAK2/STAT3 pathway." (PMID 40075566, 2025). "First, PYCR1 knockdown has been shown to inhibit proliferation, drug resistance and EMT by affecting the STAT3-mediated p38 MAPK and NF-κB pathways in colorectal cancer cells." (PMID 41254241, 2025). "While this study demonstrates promising results in the combination treatment for the inhibition of colorectal cancer cells, it primarily focuses on the JAK/STAT3 signaling pathways." (PMID 40004944, 2025). "In colorectal cancer, NR1H4 activation suppresses the JAK2/STAT3 signaling pathway via trans-activation of the suppressor of cytokine signaling 3 (SOCS3) gene and antagonizes Wnt/β-Catenin signaling, acting as a tumor suppressor." (PMID 40656893, 2025). "The nuclear translocation of STAT3 mediated by PKM2, along with the protein kinase activity of dimeric PKM2, is critical for colorectal cancer cell migration and adhesion." (PMID 40057191, 2025). "Treatment of colorectal cancer cell lines with 15 and 10 μM oleocanthal led to a dose-dependent inhibition of JAK 1/2 and STAT3 activation, respectively." (PMID 41156614, 2025). "In colorectal cancer, convallatoxin suppresses proliferation and angiogenesis via cooperation between the mTOR/STAT3 and JAK2/STAT3 pathways." (PMID 40321161, 2025). "In colorectal cancer HCT116 and HT29 cells, ursolic acid similarly decreased STAT3 phosphorylation and nuclear translocation." (PMID 41373772, 2025). "Lipopolysaccharide has been shown to increase the PKM2 expression and STAT3 promoter binding, leading to TNF-α and IL-1β production in colorectal cancer." (PMID 40982322, 2025). "Conversely, Actinomyces-induced interleukin-6 (IL-6) secretion may activate the JAK2/STAT3 pathway, increasing hepcidin production and systemic iron sequestration, a mechanism analogous to gut microbiota-mediated inflammatory pathways observed in colorectal cancer progression." (PMID 40149653, 2025).
colorectal cancer (continued). "In colorectal cancer (CRC) cell lines, B7-H3 has been shown to enhance resistance to apoptosis through the upregulation of the JAK2/STAT3 signaling pathway, resulting in an increased expression of anti-apoptotic proteins such as Bcl-2 and Bcl-xL." (PMID 40214484, 2025). "For example, HMGA2 binds to the signal transducer and activator of transcription 3 (STAT3) promoter to activate its transcription and promote macrophage recruitment in colorectal cancer (CRC)." (PMID 40475780, 2025). "The findings of this study demonstrate that STA exerts an inhibitory effect on colorectal cancer liver metastasis by targeting macrophages and impeding their M2 polarization via the JAK2/STAT3 pathway." (PMID 39974738, 2025). "In colorectal cancer (CRC), piR-54265 specifically binds to PIWIL2 and promotes the formation of the PIWIL2/STAT3/phospho-SRC complex and phosphorylation of STAT3, thereby promoting the proliferation and metastasis of CRC cells." (PMID 38915084, 2024). "Bruceantinol, a recently reported STAT3 DBD selective inhibitor, dramatically attenuates the proliferation of colorectal cancer (CRC) cells with a nanomolar concentration." (PMID 38245798, 2024). "The circular RNA circSPARC was found upregulated in colorectal cancer, where it served as a competing endogenous RNA to combine with miR-485-3p, thus elevating JAK levels, STAT3 phosphorylation, and STAT3 nuclear translocation." (PMID 38273295, 2024). "Human colorectal cancer-derived MSCs enhanced the growth and metastasis of colorectal cancer cells in vitro and in vivo via the IL-6/JAK2/STAT3 signaling pathway." (PMID 38951845, 2024). "We observed significant differences in the expression levels of STAT3 and MYC in colorectal cancer tissues." (PMID 39830506, 2024). "It has further been shown that CD276 (B7-H3) increases the ability of colorectal cancer cell lines to resist apoptosis by activating the Janus kinase 2-signal transducer and activator of transcription 3 (JAK2-STAT3) pathway." (PMID 39911580, 2024). "Elevated CHAC1 is associated with the induction of ferroptosis, highlighting the role of STAT3 as a modulator of CHAC1 and ferroptosis in colorectal cancer cells." (PMID 39534397, 2024). "TQ effectively induces apoptosis, inhibits cell proliferation, and reduces metastasis in colorectal cancer cells by modulating key molecular pathways such as PI3K/AKT/mTOR, NF-κB, STAT3, and MAPK." (PMID 39769996, 2024). "In colorectal cancer, PIWIL2 has been shown to interact with STAT3 and phospho-SRC leading to STAT3 phosphorylation and an increase in the proliferation, metastasis and chemoresistance of colorectal cancer cells." (PMID 38303021, 2024). "In colorectal cancer (CRC), CPEB3 is involved in the crosstalk between cancer cells and TAMs by targeting IL-6R/STAT3 signalling." (PMID 38987822, 2024). "piR-54265 interacts with PIWI2 to form the PIWI2/STAT3/p-SRC complex and promotes the malignant phenotype of colorectal cancer cells by increasing STAT3 phosphorylation." (PMID 38182573, 2024). "In colorectal cancer, E2F3 acts as a promoter-regulated factor, exacerbating tumor occurrence during colorectal cancer progression through the STAT3 pathway." (PMID 39045407, 2024). "In colorectal cancer, EMT and stemness maintenance were controlled simultaneously by inducing the IGF/STAT3/NANOG/Slug axis." (PMID 37660003, 2023). "The molecular mechanism utilized by METTL3 to regulate JAK1 and STAT3 expressions has been elucidated in colorectal cancer cells, but the downstream effector that orchestrated JAK/STAT3 signaling function in cancer cells is still obscure." (PMID 38001065, 2023). "In summary, our work has demonstrated that METTL3 promoted colorectal cancer progression through upregulating JAK1 and STAT3 expression in m6A-dependent and -independent manners, contributing to the activation of the p-STAT3 signaling pathway." (PMID 38001065, 2023).
colorectal cancer (continued). "In colorectal cancer, elevated levels of reactive oxygen species (ROS) disrupt glycolysis and PKM2-dependent phosphorylation of STAT3, thereby inhibiting the differentiation of Th17 cells." (PMID 37680632, 2023). "In colorectal cancer (CRC), TAMs induce EMT program to enhance CRC migration, invasion, and CTC-mediated metastasis by regulating the JAK2/STAT3/miR-506-3p/FoxQ1 axis, which in turn leads to the production of CCL2 that promote macrophage recruitment." (PMID 36817086, 2023). "Other suggested mechanisms of garcinol’s anticancer effect is interference with NF-κB, iNOS, COX-2 (especially in the inflammatory-induced cancers, such as colorectal cancer), VEGF, and signal transducer and activator of transcription 3 (STAT-3) pathway." (PMID 37359709, 2023). "IL-6 is a main proinflammatory cytokine that activates signal transducer and activator of transcription 3 (STAT3), and has a key role in the pathogenesis of UC and the carcinogenesis of colorectal cancers related to UC." (PMID 38091316, 2023). "The pathogenesis of colorectal cancer is complex and heterogeneous, with the involvement of multiple cellular transduction cascades, including AKT and STAT3 pathways." (PMID 35056682, 2022). "Further, these visceral adipose-derived factors promoted vasculogenesis and metastatic dissemination by activating the STAT3 pathway, which inhibited miR-200a and enhanced ZEB2 expression in colorectal cancer cells." (PMID 36550571, 2022). "In colorectal cancer, TFF3 promotes proliferation, invasion, and migration by enhancing CD147–CD44 interaction to activate transcription 3 (STAT3) and prostaglandin G/H synthase 2 (PTGS2) expression." (PMID 35626334, 2022). "This study aimed to synthesize new thioderivative chalcones and analyze their impact on the NF-κB, STAT3, EGFR and Nrf2 signaling pathways in colorectal cancer cells." (PMID 36050500, 2022). "At the molecular levels, this coincided with the downregulation of Nfkb1, Snai1 and Stat3 mRNA, in line with our previous study showing that PA and Cer were powerful inhibitors of an IL-10-STAT3-NF-κB signaling axis regulating EMT in colorectal cancer." (PMID 35457057, 2022). "The most successful small molecule STAT3 inhibitor Napabucasin (BBI-608), which selectively binds to the DNA-binding domain of STAT3, has reached phase III trials for advanced colorectal cancer and provided excellent results as monotherapy." (PMID 35865518, 2022). "EGCG inhibited the microenvironment-induced angiogenesis of colorectal cancer through the Janus kinase/signal transducer and activator of transcription 3/interleukin-8 (JAK/STAT3/IL-8) pathway and inhibited the invasion and metastasis of colorectal cancer." (PMID 36232338, 2022). "In summary, we found that ICAM-1 secreted from CAFs enhances the migration and invasion ability of colorectal cancer cells by activating the AKT and STAT3 pathway in cancer cells." (PMID 36016615, 2022). "Lines of evidence also indicate that STAT3 may serve as a negative regulator of ferroptosis, as suppression of STAT3 activity induces ferroptosis in gastric cancer, while ectopic expression of STAT3 rescues colorectal cancer cells from propofol-triggered ferroptosis." (PMID 36232407, 2022). "To date, there has been limited efficacy demonstrated with single-agent STAT3 inhibitor therapy, Napabucasin (BBI608) in colorectal cancer patients (Clinical Trial NCT01830621)." (PMID 35053592, 2022). "In colorectal-cancer-cell, EGCG activates caspase-3 for apoptosis, PARP, downregulation of STAT3 and phosphorylated STAT3 (p-STAT3), decreased Bcl-2 MCL-1, vimentin, along with the increase in E-cadherin." (PMID 36247004, 2022). "In our study, we found that ICAM-1 derived from MTCAFs promotes the migration and invasion of colorectal cancer cells by binding LFA-1 receptor of colon cancer, subsequently activating AKT and STAT3 in HCT116 cells." (PMID 36016615, 2022).
colorectal cancer (continued). "It has been found that wogonin inhibits the proliferation of human colorectal cancer cells by inducing autophagy, apoptosis, and G2/M cell cycle arrest via modulating the PI3K/AKT and STAT3 signaling pathways." (PMID 35178099, 2022). "ICAM-1 secreted from MTCAFs enhances the migration and invasion ability of colorectal cancer cells by activating the AKT and STAT3 pathway in cancer cells." (PMID 36016615, 2022). "Avra bacterial protein was noted to increase the activation of the STAT-3 pathway continuously, and other STAT-3 genes were noted to be involved in colorectal cancer pathogenesis." (PMID 36465770, 2022). "In radiotherapy‐resistant advanced colorectal cancer tissues, the JAK2/STAT3 signaling pathway plays a role in promoting tumorigenesis and drug resistance by inhibiting cell apoptosis and enhancing cell cloning potential." (PMID 33788424, 2021). "The JAK2/STAT3 signaling pathway mediates the function of solute carrier family 6 member 14 (SLC6A14) to promote the proliferation and metastasis of colorectal cancer cells." (PMID 34895038, 2021). "Similar to our result, other researchers have indicated that histone deacetylase inhibitor TSA suppresses the growth of colorectal cancer cells, and induces apoptosis through SOCS1 and SOCS3 upregulation and JAK2/STAT3 signaling inhibition." (PMID 34319031, 2021). "In colorectal cancer cells, the abundantly expressed lncRNA FEZF1-AS1 binds and stabilizes PKM2, thereby activating the STAT3 signaling pathway and increasing glycolysis and dissemination potential of malignant cells." (PMID 34298698, 2021). "In summary, our results present the first evidence of the anti-proliferation and anti-migration effects of EGCG against colorectal-cancer SW480, SW620, and LS411N cells by downregulating the expression of STAT3." (PMID 33747527, 2021). "In advanced colorectal cancer, the JAK2/STAT3 signaling pathway can regulate the growth of cancer stem cells and even reverse the effects of radiotherapy, contributing to resistance to radiotherapy." (PMID 33788424, 2021). "In colorectal cancer, PLK3 inhibits glucose metabolism by targeting HSP90/STAT3/HK2 signal transduction." (PMID 34217310, 2021). "Nevertheless, the compounds directly inhibiting STAT3 significantly reduced SNAIL expression and diminished EMT in osteosarcoma cells and colorectal cancer." (PMID 33478150, 2021). "For example, epidermal growth factor (EGF) increases the activation of STAT3 through its phosphorylation, thus inducing HIF-1α upregulation and promoting the proliferation and metastasis of colorectal cancer cells." (PMID 34365889, 2021). "Specific inactivation of tyrosine kinase receptors, mediated by phospholipase C (PLC), as well as a signal transducer and activator of transcription 3 (STAT3), leads to a decrease in claudin-3 levels in colorectal cancer." (PMID 34638619, 2021). "In colorectal cancer tissue samples, HOP expression correlated with STAT3 signaling, poor survival, and advancing stages of cancer, whereas HOP knockdown in colorectal cancer cells reduced proliferation, invasion, and migration." (PMID 34831344, 2021). "PKM2-mediated STAT3 nuclear translocation and the dimeric form of PKM2 showing protein kinase activity are also essential for colorectal cancer cell migration and adhesion." (PMID 33292198, 2020). "In colorectal cancer, HSPH1 promoted the phosphorylation and activation of STAT3 through a direct interaction with STAT3." (PMID 32091104, 2020). "Nuclear dimeric PKM2 also directly phosphorylates signal transducer and activator of transcription 3 (STAT3) at Tyr705, resulting in aggressive progression of colorectal cancer." (PMID 33324209, 2020).
colorectal cancer (continued). "MEK blockage has poor clinical outcome in KRAS-mutant (KRASMT) colorectal cancer cells, and siRNA-mediated knockdown of macrophage inhibitory factor (MIF) restored sensitivity to refametinib by decreasing STAT3 phosphorylation." (PMID 32872659, 2020). "In colorectal cancer, through the Janus kinase (JAK2)/signal transducer and activator of transcription (STAT3) signaling pathway, activation of α7-nAChR in tumor macrophages inhibits colorectal cancer metastasis." (PMID 33299855, 2020). "Recent evidence revealed that miR134 induces apoptosis, and inhibits proliferation and migration by targeting the STAT3 in bladder cancer cells, and miR134 abrogates proliferation and EMT in renal cell carcinoma and colorectal cancer cells." (PMID 31248140, 2019). "Although this data does not implicate a causal relationship, it further suggests a connection between STAT3 and IRF9 expression in colorectal cancer." (PMID 30679726, 2019). "It was shown furthermore, that in colorectal cancer cells, PTX3 is silenced by epigenetic modifications within these regions, that are, among other factors, induced by a high activity of STAT3 in these cells." (PMID 30774632, 2019). "Thus, STAT3 as a therapeutic target for colorectal cancer may provide a new therapeutic strategy." (PMID 31299960, 2019). "Reconstituted HDL (rHDL) nanoparticles were utilized to deliver STAT3 siRNA or FAK siRNA to treat human ovarian and colorectal cancer cell lines." (PMID 30847297, 2019). "We also investigated the activation and expression of STAT3 and IRF9 in 2D compared to 3D cultures in the colorectal cancer cell line DLD1." (PMID 30679726, 2019). "The multi-targeted TKI ponatinib was shown to inhibit STAT3 phosphorylation driven by EGFR and interleukin 6, leading to suppression of colorectal cancer cell growth and migration." (PMID 31422383, 2019). "In this study we found that transcription factor STAT3 is activated upstream of IRF9 and binds to the IRF9 promoter in MCS of HCT116 colorectal carcinoma cells." (PMID 30679726, 2019). "Of note, ursolic acid attenuated the expression of anti-apoptotic proteins such as Janus kinase 2 (JAK2) and signal transducer and activator of transcription 3 (STAT3) and also blocked nuclear translocation of STAT3 in colorectal cancer cells." (PMID 30597956, 2018). "Western blotting analysis revealed that CC-MSC-CM resulted in increased phosphorylation of JAK2, STAT3, and AKT in colorectal cancer cells; all three were activated by stimulation with IL-6." (PMID 29348540, 2018). "The crosstalk of IL-6/STAT3 and SphK1/S1P/S1PR pathways has been suggested to play an essential role in the progression of inflammation related tumors, such as colorectal cancer." (PMID 29643998, 2018). "Moreover, the studies have also shown that CXCL/CXCR and PI3K/AKT/STAT3 signaling pathways participate in the regulation of EMT- and cancer stem cell- associated events, and up-regulate the expression of Snail, Twist, ZEB1, Oct4, Sox2, c-Myc, Nanog and KLF4 in colorectal cancers." (PMID 28350360, 2017). "In colorectal cancers, miRNAs have shown involvement in, or directly regulating, oncogenic signaling pathways, such as Wnt, Ras, TGF-β, and NF-κB/AKT/STAT3 signaling pathways." (PMID 28441730, 2017). "STAT3 protein (downstream of JAK2) was found to be over-expressed and persistently activated in alimentary canal cancers, such as esophageal, stomach and colorectal cancers." (PMID 28186962, 2017). "We previously reported that IL-6R, STAT3 and miR-34a form a positive feedback-loop, which promotes epithelial to mesenchymal transition (EMT), invasion, and metastasis of colorectal cancer (CRC)." (PMID 26091352, 2015). "Our results demonstrate that LPA increases the proliferative potential of colorectal cancer HCT-116 cells through a mechanism involving cooperation between the Rho-ROCK and STAT3 pathways involved in cell cycle control." (PMID 26418031, 2015).